ALB (albumin)
Diseases named in the same sentence as ALB in open-access papers (continued):
Sharing a sentence is not in itself a finding about the gene and the disease.
Sepsis (continued). "To date, data related to the prognostic value of RAR for sepsis are scarce, and it remains to be proven whether combining the RDW with albumin level can more precisely predict the mortality of patients with sepsis relative to the RDW alone." (PMID 38877408, 2024). "Previous studies have reported similar findings, showing that albumin therapy improved the 7-day survival rate in cirrhosis patients with sepsis, but did not lead to improved 28-day survival rates." (PMID 39434907, 2024). "Another post-hoc multicenter RCT analysis of albumin replacement in severe sepsis or septic shock (ALBIOS) reported a decrease of soluble VE-cadherin in the cohort receiving albumin but no significant changes in S1P and syndecan-1." (PMID 38658435, 2024). "The results of the univariate analysis indicated that the sepsis group exhibited lower ALB concentration compared to the non-sepsis group." (PMID 38771840, 2024). "The lactate dehydrogenase (LDH) to albumin ratio (LAR), expressed as LDH/albumin, is a recently proposed biomarker that shows promise in predicting outcomes in various disease states, including cancer, liver disease, and sepsis." (PMID 38584822, 2024). "The early detection of sepsis in diabetic individuals with UTI may be achieved using a comprehensive analysis of CRP, WBC, and ALB test findings." (PMID 38771840, 2024). "Mrp 8/14, in combination with APACHE II and albumin, might improve the predictive accuracy for ICU mortality after sepsis-induced ARDS patients." (PMID 39686985, 2024). "The early detection of sepsis in diabetic individuals with urinary tract infection may be achieved by using a combination of CRP, WBC, and ALB test findings." (PMID 38771840, 2024). "Additionally, the levels of Neu%, PCT, CRP, AST, DBiL, Cr, eGFR, and Ur in the sepsis group were significantly higher than in the non-sepsis group, while the levels of PLT and ALB were significantly lower (p < 0.05)." (PMID 39457503, 2024). "Our study has revealed that serum albumin levels in patients suffering from sepsis do not invariably remain stable; a minority of patients exhibit rapid fluctuations (G2)." (PMID 39101009, 2024). "For that reason, the routine administration of albumin in this patient cohort is not recommended in the surviving sepsis campaign." (PMID 37218881, 2023). "Compared with neonates in the pneumonia group, neonates in the sepsis group were older, had a higher body temperature, respiratory rate, and heart rate, and had higher levels of PCT, CRP, ALT, and neutrophil count, and lower levels of ALB and SaO2/FiO2." (PMID 36908271, 2023). "The AUCs for PCT, ALB and CRP were 0.69 (95% CI, 0.66–0.73, p < 0.001), 0.68 (95% CI, 0.65–0.72, p < 0.001) and 0.68 (95% CI, 0.64–0.71, p < 0.001), respectively, which were lower than the AUC for PAR in predicting sepsis in neonates with pneumonia (p < 0.05)." (PMID 36908271, 2023). "We randomly chose a male patient with sepsis who age was 81 years old, LDH was 371 IU/L, potassium was 4.8 mEq/L, calcium was 11.1 mg/dL, albumin was 4 g/dL, hemoglobin was 8.9 g/dL, ALP was 159 IU/L, had not used vasopressor, Elixhauser score was 42, and had respiratory failure." (PMID 37807068, 2023). "For 90-day mortality, the treatment with albumin resulted in a lower rate compared to crystalloids for patients with septic shock but not for those with severe sepsis." (PMID 37779759, 2023). "While the majority of current research specifies the need for additional studies, it has become clear that albumin may have a role as a niche drug in specific patient populations, such as those with ARDS and sepsis." (PMID 36909040, 2023). "In systemic inflammation and sepsis, trauma or inflammation, the synthesis of the negative acute-phase proteins, including albumin, is reduced." (PMID 37342623, 2023).
Sepsis (continued). "This aligns with the observation of data indicating that in sepsis, the binding capacity of reversibly oxidized albumin known as human nonmercaptalbumin-1 (HNA-1) is impaired as determined by assessments using different techniques." (PMID 37628734, 2023). "In this study, our data showed that neonates with sepsis had a higher PCT level and a lower ALB level, indicating that PCT and ALB may aid in the earlier identification of sepsis in neonates with pneumonia." (PMID 36908271, 2023). "The prospective study design, the collection of albumin at the first medical evaluation in the ED, and the cohort of patients with infections, not sepsis alone, are novelties provided by the study." (PMID 37240554, 2023). "Acute physiology score III (APSIII), sepsis related organ failure assessment (SOFA), international normalized ratio (INR), total bilirubin (TBIL), albumin, blood urea nitrogen (BUN), acute kidney injury (AKI) and mechanical ventilation were identified as independent risk factors." (PMID 37024814, 2023). "This hypothesis is also supported by our observations that functional parameters, which describe albumin’s binding capacity, such as ABiC, BE, and DTE, were reduced among patients suffering from sepsis or septic shock when compared to the control group." (PMID 37628734, 2023). "There are currently no studies to show if albumin treatment during sepsis can improve lung health and prevent the development of ARDS." (PMID 36909040, 2023). "In the sepsis-negative group, pH, LD, creatinine, bicarbonate, albumin, glucose, and BUN were statistically significant." (PMID 37626427, 2023). "Nevertheless, the relationship between ferritin/albumin levels and mortality rates in patients with sepsis is still not clear." (PMID 37817258, 2023). "Concerns regarding albumin in sepsis include the lack of clear benefits, increased costs, and safety issues such as the risks of hypervolemia, pulmonary complications, myocardial insufficiency, and hemorrhagic complications." (PMID 38139434, 2023). "In line with this reasoning, albumin reduced 90-day mortality in septic shock patients, while this was not witnessed in patients with sepsis and no shock." (PMID 37728777, 2023). "Systematic reviews and meta-analyses followed and showed an increased risk for adverse events, blood transfusions, acute renal failure, and a potential increase in mortality with HES compared to crystalloids or albumin, marking the end of the HES era in sepsis." (PMID 37764075, 2023). "To make our results more reliable, we also performed subgroups based on sepsis since inflammation may play a role in determining RDW and albumin status." (PMID 36968820, 2023). "Albumin is not recommended as the first-line fluid for resuscitation in sepsis due to the lack of proven benefit and its higher cost compared to crystalloids." (PMID 37374251, 2023). "These predictive features include the primary reason for ICU admission (medical reason (i.e., sepsis) vs. surgical problem (i.e., postoperative care)), blood urea nitrogen (BUN), heart rate, PaO2/FiO2 ratio, pH, albumin, lactate, prothrombin time (PT), hemoglobin in CanICU." (PMID 36765528, 2023). "In addition, the multivariate analysis showed that age, sepsis, surgery, CRP, albumin level, lymphocyte count, Hb level, APACHE II score, duration of MV, and RBC and PLT transfusion were significantly associated with PIICS." (PMID 35022421, 2022). "The fibrinogen to albumin ratio was commonly identified as a predictor of poor outcome and adverse events in patients with cardiovascular diseases, cancer, sepsis, and stroke, although not in neurosurgical ICU-admitted ICH patients." (PMID 35887976, 2022). "Similar to their findings, several parameters in our study associated with liver function were found to be relevant to post-endoscopy sepsis in the univariate analysis (HCC, MELD score, Child score, Child–Pugh classification, ascites, HH, platelet count, PT, and serum albumin and bilirubin levels)." (PMID 35139804, 2022).
Sepsis (continued). "Patients with higher TyG index were generally younger, higher severity of illness scores on admission, higher prevalence of DM, COPD, RF, LD, AKI, CKD, sepsis, higher levels of WBC, Scr, TC, LDL, hemoglobin A1c and blood urea nitrogen, lower levels of albumin and HDL compared to the lower group." (PMID 35804386, 2022). "In addition, in the early stage of sepsis, the liver will prioritize the synthesis of acute phase proteins such as CRP over ALB." (PMID 35109818, 2022). "Human serum albumin (HSA) corrects not only hypoalbuminemia but also hypovolemia and ensures tissue perfusion, and is a commonly used drug in the clinical treatment of sepsis." (PMID 36578542, 2022). "One of the most influential prospective studies, published in 2014, was a multi-center trial of 1,818 patients with severe sepsis, which concluded that the addition of albumin did not improve the 28- or 90-days mortality compared with crystalloids alone." (PMID 35721190, 2022). "The AUC for CRP, ALB, and PCT was 0.67 (95% CI 0.64-0.71, P < 0.001), 0.70 (95% CI 0.66-0.74, P < 0.001), and 0.70 (95% CI 0.66-0.79, P < 0.001), which were lower than the AUC for CAR in predicting sepsis in neonates with pneumonia (P < 0.05)." (PMID 35873709, 2022). "Two specific proteins were upregulated in non-septic inflammation but showed no significant variations in the saliva of pigs with sepsis: ALB and histone H4." (PMID 35743177, 2022). "Among patients with serious disease conditions and sepsis, 20% albumin has been found superior to 4–5% albumin but has not consistently decreased the mortality rate as compared with the use of normal saline." (PMID 35931952, 2022). "Albumin is a negative acute-phase protein as its levels fall after injury, sepsis, and surgical stress." (PMID 35706741, 2022). "Our data provide evidence-based support to the recommendation that albumin infusions should be prescribed based on clinical indicators (i.e., anasarca, ascites, sepsis, thrombotic events), not solely the serum albumin concentrations." (PMID 36210940, 2022). "A meta-analysis of 10 studies involving 6664 patients with sepsis showed no increase in the use of RRT with albumin when compared to crystalloids." (PMID 34040918, 2021). "In the Albumin Italian Outcome Sepsis trial, albumin replacement did not improve survival at 28 and 90 days among patients with severe sepsis or septic shock." (PMID 34193271, 2021). "So far, albumin replacement studies in patients with sepsis and/or AKI did not improve outcomes, although the studied populations did not aim at hematological patients." (PMID 33704529, 2021). "The predictive value of low serum albumin is independent of the site of infection and independent of the patients’ age, even considering newborn and pediatric patients with sepsis." (PMID 33925831, 2021). "LAlb: Lower albumin (<3.5g/dl); WA: Walking ability; NU: nutritional supply requirement; ACS: Acute confusional syndrome; AK+: Hyperkalaemia; RnI: Renal Insufficiency; RsI: Respiratory insufficiency; CI: Cardiac insufficiency; SP: Sepsis; ST: Stroke." (PMID 33592047, 2021). "Consistently, we found that the elevation of plasma NPC2 concentration in sepsis patients occurs in the absence of any increase in total plasma protein or albumin, indicators of protein synthesis activity of hepatocytes." (PMID 33723331, 2021). "In ALBIOS, crystalloids supplemented with albumin were not superior to crystalloids alone in fluid replacement in patients with severe sepsis or septic shock." (PMID 33741039, 2021). "More importantly, clinical trials show that infusing albumin solutions to maintain a near-normal plasma albumin concentration in patients with severe sepsis does not confer any therapeutic advantage." (PMID 33889604, 2021). "At present, international guidelines do not recommend albumin as the first choice for resuscitation in severe sepsis or septic shock." (PMID 34916544, 2021).
Sepsis (continued). "The albumin and fibrinogen values at 72 hours after the first suspicion of sepsis showed negative path coefficients (γ = −0.189 and −0.254, respectively)." (PMID 33663106, 2021). "Arnau-Barrés has found that in elderly sepsis patients with sepsis, the non-survivors admitted to the hospital show a notably lower albumin level than survivors (2.6 vs 3.1 mg/dL, P < 0.01)." (PMID 34934165, 2021). "Related studies suggested that the half-life of albumin was 14 to 20 days, which does not indicate immediate nutritional status, while the infusion of albumin, dehydration, sepsis, and other conditions affect albumin concentration." (PMID 33429794, 2021). "To date, to the best of our knowledge, no other study unravelled the association between (albumin-adjusted) plasma-free thiols and AKI in patients in the ICU with and without sepsis." (PMID 33207555, 2020). "Albumin is considered a negative active phase protein because it decreases during injuries and sepsis." (PMID 32664910, 2020). "However, the sepsis group had higher levels of Scr, WBC, CRP, and PCT in the serum, while had lower serum albumin levels than healthy group (all P < 0.001), and the differences reached significant level." (PMID 32188465, 2020). "To our knowledge, this was the first study to investigate the prognostic value of NPAR in critically ill patients with severe sepsis or septic shock; we found that higher NPAR was a novel predictor of poorer prognosis, and it was a better predictor than either albumin or neutrophil percentage alone." (PMID 32238212, 2020). "This is the first study to use a nomogram to develop a novel prediction model that shows that WBC, anemia, PCT, CRP, albumin, and ALT may help clinicians differentiate KD from sepsis with high accuracy." (PMID 32792679, 2020). "Further, albumin-adjusted free thiol levels were significantly reduced in patients with sepsis (8.30 (5.52–10.64) μmol/g) compared to patients without sepsis (6.95 (3.72–8.92) μmol/g; p < 0.05)." (PMID 33207555, 2020). "IGFBP-7 knockout can activate ERK1/2 signaling pathway, reduce creatinine, urea nitrogen, albumin, and cell apoptosis in mice urine, and effectively reduce the severity of renal injury, indicating that IGFBP-7 regulates AKI induced by sepsis through ERK1/2 signaling." (PMID 31661774, 2019). "A conservative conclusion of all these studies is the lack of strong evidence in favor of albumin during sepsis without shock." (PMID 30374936, 2018). "In contrast, the ALBIOS study of targeted albumin replacement in sepsis found neither nephrotoxicity nor mortality difference with albumin replacement." (PMID 30564306, 2018). "Post hoc analyses, with their inherent limitation, suggested a trend for higher mortality in patients with severe sepsis without shock who received albumin and a significant reduction in mortality with albumin in patients with septic shock." (PMID 30374936, 2018). "The C-reactive protein/albumin ratio (CAR), represented as a combination of serum CRP and ALB counts, was initially used as a new inflammation-based prognostic score for the purpose of predicting mortality in patients with sepsis." (PMID 29568406, 2018). "In 44 newborns with sepsis, MDA, SOD, GPx, and CAT were significantly increased in comparison to controls, while uric acid and albumin levels were significantly reduced, and similar changes were also observed in those newborns who died because of sepsis in comparison to survivors." (PMID 30174784, 2018). "These negative findings of albumin use in children with sepsis are in contrast to the non-significant but more favorable findings in adults with sepsis." (PMID 28729906, 2017). "We tested these novel solutions with and without the addition of albumin and compared them to traditional fluids in a mouse model of early sepsis induced by cecal ligation and puncture (CLP)." (PMID 28105603, 2017).
Sepsis (continued). "Since sinusoidal blood flow was significantly decreased in response to sepsis for all resuscitation fluids, these findings suggest that the osmotic effects of albumin are not sufficient to restore sinusoidal blood flow in septic mice." (PMID 28105603, 2017). "Deceased AKI patients were statistically significantly older (P < 0.000), with higher CCI score (P < 0.000), greater prevalence of sepsis (P =0.004), higher levels of C-reactive protein (CRP) (P < 0.017) and ferritin (P < 0.051) and lower concentrations of albumin (P<0.01) compared to survivors." (PMID 27471736, 2016). "Specifically for patients with sepsis (patient type 3), physicians from university hospitals were the more likely to prefer albumin compared to physicians from nonuniversity hospitals." (PMID 27313844, 2016). "Among patients in the SPD group, the main acute comorbid conditions were peripheral vascular and cardiac complications, sepsis, fractures, and cancers with an increase in serum CRP level (from 14.3 ± 18 to 132 ± 90 mg/L) and a decrease in serum albumin (from 33 ± 4.5 to 28.6 ± 4 g/L)." (PMID 27756251, 2016). "Despite the supposed beneficial effect of albumin in experimental studies, in patients with severe sepsis, albumin replacement in addition to crystalloids did not improve outcome." (PMID 27699168, 2016). "These factors are of decreased predictive utility in the LT candidate population in which low albumin, functional dependence, and high ASA class are common; and active, uncontrolled sepsis may temporarily inactivate status on the wait list." (PMID 27980860, 2016). "Furthermore, we did not expect to see more physicians prefer HES 450/600 (6–10 %) over 25 % albumin (5–7 %), as the use of HES for patients with sepsis goes against the Surviving Sepsis Campaign (SSC) recommendations." (PMID 27313844, 2016). "With each 1 L/m2 increase in the TBW/H2, in-hospital mortality increased by 31.2% when adjustments were made for age, BMI, the presence of sepsis, SOFA score, actual CVVHDF dose, CVVHDF initiation time, PT and serum albumin levels in a binary logistic regression analysis." (PMID 26186370, 2015). "Immediately after CLP-sepsis surgery (30 mins), pulmonary microvascular endothelial EB-albumin permeability was slightly, but not significantly greater than in sham mice, at 1.4 ± 0.3 μg EB/g lung/min." (PMID 26376777, 2015). "Since crystalloids in fluid resuscitation of sepsis patients do not lead to stable hemodynamics, the natural colloid albumin should be additionally used according to the guidelines." (PMID 26136776, 2015). "Controversially, a recent multicenter, open-label trial observed that albumin replacement in addition to crystalloids did not improve the survival rate of patients with severe sepsis." (PMID 26557421, 2015). "This explains why albumin infusion, despite showing a better ‘volemic’ effect, is not able to resolve the interstitial edema in patients with sepsis." (PMID 25887223, 2015). "Factors independently associated with the occurrence of any post-operative complication included: age, female gender, ASA class, pre-operative sepsis, COPD, low serum albumin concentration, pre-operative radiotherapy, pre-operative transfusion >4 units, and operative time >6 hours (all p<0.05)." (PMID 25360904, 2014). "Nevertheless, in the same study, sepsis, a low albumin level, and malignancy, but not hypoglycemia, were found to be independent predictors of mortality by multivariate analysis." (PMID 25147737, 2014). "In Sub-Saharan African children with severe sepsis, fluid boluses with saline or 5% Albumin in saline result in increased mortality when compared to no fluid boluses." (PMID 25180196, 2014). "Compared with crystalloid, albumin displayed no beneficial effect on 28-day mortality in severe sepsis patients (OR 0.93; 95% CI, 0.80 to 1.08; P = 0.32)." (PMID 25499187, 2014).